GPIHBP1 (glycosylphosphatidylinositol anchored high density lipoprotein binding protein 1)
Description:
Mediates the transport of lipoprotein lipase LPL from the basolateral to the apical surface of endothelial cells in capillaries (By similarity). Anchors LPL on the surface of endothelial cells in the lumen of blood capillaries (By similarity). Protects LPL against loss of activity, and against ANGPTL4-mediated unfolding. Thereby, plays an important role in lipolytic processing of chylomicrons by LPL, triglyceride metabolism and lipid homeostasis. Binds chylomicrons and phospholipid particles that contain APOA5. Binds high-density lipoprotein (HDL) and plays a role in the uptake of lipids from HDL (By similarity).
Synonyms: GPI-HBP1; LOC338328; HYPL1D
Tractability: Small molecule: a structure with a bound ligand is known. Antibody: UniProt places it where antibodies can reach, with high confidence; its Gene Ontology location is reachable by antibodies, with high confidence; UniProt predicts a signal peptide or a membrane-spanning region.
Gene: Protein-coding gene on chromosome 8 (143,213,019 to 143,217,172, forward strand). Ensembl gene ENSG00000277494.
Subcellular location: Apical cell membrane; Basolateral cell membrane; Cell membrane
Subcellular location (Human Protein Atlas): End piece; Principal piece
Pathways (Reactome):
Transport of small molecules: Assembly of active LPL and LIPC lipase complexes; Chylomicron remodeling
Metabolism of proteins: Post-translational modification: synthesis of GPI-anchored proteins
Sensory Perception: Retinoid metabolism and transport
Gene Ontology:
Molecular function: chylomicron binding; lipase binding; lipoprotein lipase activator activity; lipoprotein particle binding; protein binding; protein carrier chaperone
Biological process: positive regulation of fatty acid biosynthetic process; protein stabilization; response to heparin; triglyceride catabolic process; triglyceride homeostasis; cholesterol homeostasis; intracellular protein transport; positive regulation of chylomicron remnant clearance; positive regulation of chylomicron remodeling; positive regulation of lipid transport; protein import; protein localization to cell surface; transcytosis
Cellular component: catalytic complex; external side of plasma membrane; plasma membrane; apical plasma membrane; basolateral plasma membrane; extracellular region
Genetic constraint (gnomAD): Loss-of-function variants: 11 observed, 10.19 expected, observed/expected ratio (o/e) 1.08, 90% interval 0.68 to 1.72. The upper end of that interval is the gene's LOEUF score, 1.72, which puts it in group 6 of 6, group 1 being the genes least tolerant of losing a copy. Missense variants: 226 observed, 227.93 expected, observed/expected ratio (o/e) 0.99, 90% interval 0.89 to 1.11. Synonymous variants: 105 observed, 96.96 expected, observed/expected ratio (o/e) 1.08, 90% interval 0.92 to 1.27.
Homologues: Orthologues: chimpanzee GPIHBP1 (98% identical), macaque GPIHBP1 (85% identical), dog GPIHBP1 (56% identical), guinea pig GPIHBP1 (54% identical), mouse Gpihbp1 (54% identical), pig GPIHBP1 (53% identical), rat Gpihbp1 (47% identical). Paralogues in human: LY6E (22% identical), PSCA (19% identical).
Diseases named in the same sentence as GPIHBP1 in open-access papers:
GPIHBP1 is named in the same sentence as 55 diseases in open-access papers, as found by Europe PMC text mining. Sharing a sentence is not in itself a finding about the gene and the disease. The quoted sentences say what the papers report.
hypertriglyceridemia (48 papers, 2007 to 2026). A laboratory test result indicating elevated triglyceride concentration in the blood. "This case illustrates hypertriglyceridemia caused by a rare disease entity associated with autoantibodies against the GPIHBP1 protein." (PMID 41783132, 2026). "Mutations in GPIHBP1 have been associated with severe hypertriglyceridaemia, which results in an increased risk of acute pancreatitis, underscoring the importance of GPIHBP1 in intravascular TG processing." (PMID 41142641, 2025). "Disabling trans-capillary LPL transport by inhibitory GPIHBP1 autoantibodies also causes hypertriglyceridemia." (PMID 39814316, 2025). "Bi-allelic loss-of-function variants in LPL or in other genes promoting LPL activity in the capillary lumen (e.g., APOC2, APOA5, LMF1, GPIHBP1) cause severe hypertriglyceridemia with a predisposition to acute pancreatitis." (PMID 39814316, 2025). "If the function of GPIHBP1 is disabled by either bi-allelic loss-of-function variants or by inhibitory autoantibodies the affected individuals develop severe hypertriglyceridemia with a risk for life-threatening pancreatitis." (PMID 39814316, 2025). "In this study, circulating GPIHBP1 levels during pregnancy were evaluated, and their associations with hypertriglyceridaemia and the perinatal outcomes of GDM were evaluated." (PMID 41142641, 2025). "GPIHBP1-AAS–associated hypertriglyceridemia should be recognized and can be successfully treated with rituximab." (PMID 40816829, 2025). "Detailed biochemical–clinical–genetic characterization of primary hypertriglyceridemia; identified 74 variants; first Mexican case of hyperchylomicronemia syndrome due to GPIHBP1 deficiency." (PMID 40428368, 2025). "This study assessed circulating GPIHBP1 levels during pregnancy and investigated their associations with hypertriglyceridaemia and perinatal outcomes in cases of GDM." (PMID 41142641, 2025). "GPIHBP1 deficiency in humans causes lifelong hypertriglyceridemia, with plasma TG levels greater than 1,500 mg/dL." (PMID 39435661, 2024). "In mammals, GPIHBP1 deficiency causes severe hypertriglyceridemia, but chickens maintain low triglyceride levels despite the absence of GPIHBP1." (PMID 39435661, 2024). "The null mutation of GPIHBP1 causes severe hypertriglyceridemia and pancreatitis, and GPIGBP1 autoantibody syndrome also causes severe hypertriglyceridemia and recurrent episodes of acute pancreatitis." (PMID 37448184, 2023). "The null mutation of GPIHBP1 and the production of GPIHBP1 autoantibody induce severe hypertriglyceridemia and recurrent episodes of acute pancreatitis." (PMID 37448184, 2023). "In the case with recurrent episodes of severe hypertriglyceridemia and acute pancreatitis, intermittent hypertriglyceridemia was caused by intermittent appearance of GPIHBP1 autoantibodies." (PMID 37448184, 2023). "The acquired cases with severe hypertriglyceridemia caused by GPIHBP1 autoantibodies were discovered by the screening of the patients with unexplained hypertriglyceridemia." (PMID 37448184, 2023). "Patients with missense mutations of GPIHBP1 have been reported, and they showed severe hypertriglyceridemia, recurrent acute pancreatitis and other complications." (PMID 37448184, 2023). "Hypertriglyceridemia (HTG) has been recently added to its side effect profile with a possible pathogenic mechanism involving autoantibodies against glycosylphosphatidylinositol-anchored high-density lipoprotein binding protein 1 (GP1HBP1)." (PMID 37261185, 2023). "The heterozygous variant c.41G > T in GPIHBP1 has been associated with hypertriglyceridemia and is likely benign, as the minor allele frequency for the c.41G > T variant is 29% in East Asian population according to the Genome Aggregation Database." (PMID 36312279, 2022). "Our paediatric patient had a homozygous pathogenic GPIHBP1 variant, causing severe hypertriglyceridemia, cholesterol deposits at the hard palate, eruptive xanthomas, lethargy, poor appetite, and mild splenomegaly." (PMID 36051701, 2022).
hypertriglyceridemia (continued). "Deficiency in either LPL or GPIHBP1 impairs TG hydrolysis, resulting in severe hypertriglyceridemia." (PMID 34036306, 2021). "Recent reports have demonstrated that GPIHBP1 autoantibodies and gene mutations cause hypertriglyceridemia." (PMID 30947712, 2019). "We previously showed the importance of GPIHBP1 in TG homeostasis is illustrated by the identification of patients with severe hypertriglyceridemia who have a homozygous loss-of-function mutation in GPIHBP1." (PMID 30408040, 2018). "Studies of Gpihbp1−/Gpihbp1− knock out mice have shown that GPIHBP1-deficiency causes severe hypertriglyceridemia with very high plasma triglyceride levels of 2,000–5,000 mg/dl." (PMID 22582156, 2012). "Genetic ablation of Gpihbp1 reduces vascular presentation of Lpl and plasma levels of Lpl activity and mass, which causes striking hypertriglyceridemia." (PMID 21085708, 2010). "Some acquired forms of hypertriglyceridemia are caused by inhibitory GPIHBP1 autoantibodies." (PMID 39435661, 2024). "Thus, a very rare GPIHBP1 missense mutation appears to be associated with severe hypertriglyceridemia and chylomicronemia." (PMID 17883852, 2007). "Glycosylphosphatidylinositol-anchored high-density lipoprotein-binding protein 1 (GPIHBP1) is an anchor protein of LPL in the vascular endothelium, and autoantibodies against GPIHBP1 can decrease the LPL activity levels to cause hypertriglyceridemia." (PMID 41156460, 2025). "GPIHBP1-AAS was only recently described and is associated with severe hypertriglyceridemia and recurrent pancreatitis." (PMID 40816829, 2025). "GPIHBP1-AAS has been described only recently and is associated with severe hypertriglyceridemia and recurrent pancreatitis in the literature." (PMID 40816829, 2025). "The profound hypertriglyceridemia in Gpihbp1–/– mice contrasts with the situation in chickens, where GPIHBP1 is absent but plasma TG levels are less than 100 mg/dL, even on a fat-enriched diet." (PMID 39435661, 2024). "GPIGBP1 autoantibody syndrome was found in the patients with multiple sclerosis treated with interferon β1a, who developed severe hypertriglyceridemia and very low plasma levels of GPIHBP1 and LPL." (PMID 37448184, 2023). "In this review, we focus on the recently identified GPIHBP1, and describe the biological function, relevance in hypertriglyceridemia and new insights in the diabetic vascular complications." (PMID 37448184, 2023). "Various GPIHBP1 mutations have been found to prevent GPIHBP1 from binding LPL, resulting in invalid processing of TG and severe hypertriglyceridemia." (PMID 35741760, 2022). "For severe hypertriglyceridemia, pathogenic variants in genes LPL, APOA5, APOC2, GPIHBP1, and LMF1, associated with hyperlipidemia should be considered." (PMID 36051701, 2022). "Most variants interfering with triglyceride metabolism and causing hypertriglyceridemia are loss of function variants (LOF), and mainly found in the LPL, APOC2, APOA5, LMF1 and GPIHBP1 genes." (PMID 35237305, 2022). "A set of 53 single nucleotide polymorphisms (SNPs) previously associated with triglycerides levels, as well as 37 rare variants within the five main genes associated with hypertriglyceridemia (i.e. LPL, APOC2, APOA5, LMF1 and GPIHBP1) were analyzed." (PMID 33588820, 2021). "Variants on genes known to cause severe hypertriglyceridemia such as LPL, APOC2, GPIHBP1, APOA5, and LMF1 were first selected and interpreted." (PMID 32765589, 2020). "GPIHBP1 autoantibodies block the LPL binding to GPIHBP1‐transfected Chinese hamster ovary cells, suggesting that GPIHBP1 autoantibodies functionally blocked LPL‐mediated processing of TRL, causing severe hypertriglyceridemia." (PMID 37448184, 2023). "Severe hypertriglyceridemia, in the form of Familial Chylomicronaemia Syndrome (FCS), is a rare autosomal recessive disease caused by pathogenic variants especially in the LPL gene but also in APOC2, APOA5, LMF1 and GPIHBP1." (PMID 35237305, 2022).
hypertriglyceridemia (continued). "In Mexico, hypertriglyceridemia constitutes a health problem in which the genetic bases have been scarcely explored; therefore, our objective was to describe biochemical–clinical characteristics and variants in the APOA5, GPIHBP1, LMF1, and LPL genes in patients with primary hypertriglyceridemia." (PMID 36613909, 2022). "APOA5 deficiency leads to hypertriglyceridemia, which may reflect its role in the efficient association of TRL with LPL or GPIHBP1 on endothelial cells, possibly because APOA5 interferes with an inhibitory effect of ANGPTL3/ANGPTL8 on this association." (PMID 34981790, 2022). "Furthermore, a novel role of hepatic glycosylphosphatidylinositol-anchored high-density lipoprotein binding protein 1 (GPIHBP1) was confirmed in hypertriglyceridemia with marked liver steatosis in ApcMin/+ mice." (PMID 33557173, 2021). "Although the acidic domain constitutes 30% of the primary sequence of mature GPIHBP1, no gene variants linked to hypertriglyceridemia have been localized to this region." (PMID 34336854, 2021). "Recently, GPIHBP1 auto-antibodies were shown to cause late-onset chylomicronemia by blocking the interaction between LPL and GPIHBP1 in 22 patients with a hitherto unexplained form of acquired hypertriglyceridemia." (PMID 34336854, 2021). "This binding pose aligns well with data from HDX-MS analyses and site-directed mutagenesis —and it explains why certain genetic variants of GPIHBP1 and LPL are associated with hypertriglyceridemia as they compromise the complementarity of the binding interface." (PMID 34336854, 2021). "Genetic studies revealed that homozygous or biallelic loss-of-function variants in LPL or its partners (GPIHBP1, APOC2, LMF1, APOA5) severely impair the efficiency of triglyceride hydrolysis, causing lifelong severe hypertriglyceridemia—the familial chylomicronemia syndrome." (PMID 34336854, 2021). "Because the two hypertriglyceridemia mouse models, namely, Gpihbp1−/− and ApoC3-tg mice, are generated by different genetic modifications, their TRLs may be different when representing the two types of hypertriglyceridemia." (PMID 31570698, 2019). "Therefore, Gpihbp1−/− and ApoC3-tg mice are obviously two different types of hypertriglyceridemia models with different TRL types." (PMID 31570698, 2019). "We chose two mouse hypertriglyceridemia models to mimic different hypertriglyceridemia subtypes in this study, including glycosylphosphatidylinositol-anchored high-density lipoprotein binding protein 1 knockout (Gpihbp1−/−) and apolipoprotein C3 transgenic (ApoC3-tg) mice." (PMID 31570698, 2019). "Therefore, we crossed ApoCIIItg mice and ApoCIII−/− mice with GPIHBP1−/− mice, another extreme hypertriglyceridemia mouse model, to generate two hyperlipidemia mice models: ApoCIIItgGPIHBP1−/− and ApoCIII/GPIHBP1 DKO mice, respectively." (PMID 30223835, 2018). "Variants in the lipoprotein lipase (LPL), apolipoprotein C-II (APOC2), apolipoprotein A-V (APOA5), GPIHBP1 and LMF1 genes may cause severe hypertriglyceridemia (HTG), which is now the second-leading aetiology of acute pancreatitis in China." (PMID 29921298, 2018). "However, Gpihbp1−/− mice differ significantly from Col18a1−/− mice in the extent of hypertriglyceridemia and localization of Lpl in tissues." (PMID 21085708, 2010). "Thus, GPIHBP1 dysfunction and downregulation result in hypertriglyceridemia." (PMID 40816829, 2025). "In 2 patients with hypertriglyceridemia, enzyme-linked immunosorbent assay could not identify recombinant GPIHBP1 added to their serum, suggesting immunoassay interference and an antibody present to GPIHBP1." (PMID 40816829, 2025). "Unexpectedly, however, most of the GPIHBP1 and LPL in the mutant mice was located on the abluminal surface of ECs (explaining the hypertriglyceridemia)." (PMID 35229724, 2022). "Besides LPL, there are other genes involved in primary hypertriglyceridemia phenotypes (most notably, APOC2, APOA5, LMF1, and GPIHBP1)." (PMID 36051701, 2022).
hypertriglyceridemia (continued). "With the discovery of GPIHBP1, the pathway for LPL transport and distribution in the intravascular unit changed radically and new etiologies for both inborn and acquired hypertriglyceridemia were outlined." (PMID 34336854, 2021). "No mutation in the major genes involved in severe hypertriglyceridemia (LPL, APOAV, APOCII, LMF1, GPIHBP1) was found." (PMID 35011612, 2021). "The optical density was positively associated with the triglyceride concentration in the plasma from both hypertriglyceridemia mice models, while the turbidity (shown as OD650/triglyceride) of the Gpihbp1−/− mice plasma was significantly higher than the ApoC3-tg mice plasma." (PMID 31570698, 2019). "In addition, recent reports have identified the presence of GPIHBP1 antibodies that inhibit the ability of GPIHBP1 to bind and transport LPL in patients with hypertriglyceridemia." (PMID 30947712, 2019). "In 2012, we found an excessive prevalence of rare variants in LPL, APOC2, GPIHBP1, APOA5, and LMF1 in patients with severe hypertriglyceridemia, again indicating that heterozygosity was a predisposing factor for, although not an absolute cause of severe hypertriglyceridemia or MCM." (PMID 32793115, 2020). "In Gpihbp1–/– mice, LPL is stranded within the interstitial spaces and never reaches the capillary lumen, resulting in severe hypertriglyceridemia." (PMID 39435661, 2024). "In the absence of functional GPIHBP1, LPL is mislocalized within the interstitial spaces, leading to severe hypertriglyceridemia and reduced delivery of lipid nutrients to parenchymal cells." (PMID 26725083, 2016). "LPL release from endothelial cells in response to heparin stimulation requires the activity of GPIHBP1 (GPI-anchored high-density lipoprotein binding protein 1) and primary genetic defects in this GPI-anchored protein lead to hypertriglyceridemia and non-detectable serum lipoprotein lipase." (PMID 25885527, 2015).
familial chylomicronemia syndrome (9 papers, 2020 to 2025). A rare autosomal recessive disease characterized by the buildup in the blood of fat particles called chylomicrons (chylomicronemia), severe hypertriglyceridemia, and the risk of recurrent and potentially fatal pancreatitis and other complications. "The case report contributes to the understanding of GPIHBP1-deficient familial chylomicronemia syndrome (FCS) and highlights gestational management of FCS patient." (PMID 32375710, 2020). "At the genetic level, severely elevated triglyceride levels resulting from familial chylomicronemia syndrome (FCS) are caused by homozygous or biallelic loss-of-function variants in LPL, APOC2, APOA5, LMF1, and GPIHBP1 genes." (PMID 32793115, 2020). "Familial chylomicronemia syndrome (FCS) is a rare disorder of triglyceride (TG) metabolism caused by loss of function variants in one of five known canonical genes involved in chylomicron lipolysis and clearance—LPL, APOC2, APOA5, LMF1, and GPIHBP1." (PMID 38974610, 2024). "When due to very rare monogenic mutations in the genes encoding the enzyme, lipoprotein lipase, or its regulators, APOC2, APOA5, GPIHBP1, and LMF1, it is referred to as the familial chylomicronemia syndrome." (PMID 33193106, 2020).